CXCL12 (C-X-C motif chemokine ligand 12)
Diseases named in the same sentence as CXCL12 in open-access papers (continued):
Sharing a sentence is not in itself a finding about the gene and the disease.
pancreatic cancer (continued). "For example, TAFs in gastric cancer and pancreatic cancer secrete CXCL12 and activate the CXCL12/CXCR4-pathway to promote tumor growth 34,35." (PMID 35982904, 2022). "This CXCL12 coating was investigated using a mouse model of pancreatic cancer that replicates the immunological characteristics of human cancer." (PMID 35046049, 2022). "In vitro studies of pancreatic cancer have shown that CXCL8 works synergistically with CXCL12 to promote angiogenesis and invasion." (PMID 35879507, 2022). "In pancreatic cancer, the CXCL12 chemokine derived from FAP-expressing CAFs has gained recognition as an attractive therapeutic target." (PMID 35805064, 2022). "Increased expression of CXCL12/SDF-1 by CAFs following irradiation has been also reported in pancreatic cancer, melanoma and lung cancers." (PMID 34663337, 2021). "Radiation of CAFs also promotes the secretion of high concentrations of CXCL12 both in vitro and in vivo via the P38 pathway, as such it promotes pancreatic cancer cell migration, invasion, and EMT." (PMID 33673405, 2021). "Fibroblast-derived CXCL12 in concert with pancreatic tumor-derived CXCL8 has been shown to promote proliferation, invasion, and tube formation of endothelial cells in vitro." (PMID 35008248, 2021). "In a murine model of pancreatic cancer, CXCL12 (C-X-C motif chemokine ligand 12) produced by CAF has also been show to inhibit T-cell infiltration into tumour islets." (PMID 35048030, 2021). "The role of CXCL12-mediated activation of FAK, ERK and AKT, has also been associated with chemoresistance in pancreatic cancer, among other gastrointestinal cancers." (PMID 33546207, 2021). "More strikingly, the inflammatory fibroblasts overexpressed CXCL12, and these CXCL12-expressing fibroblasts were found to encourage the immune escape of pancreatic cancer cells." (PMID 34745998, 2021). "CXCR4 also activates the Wnt and Hedgehog signalling pathways to express the EMT phenotype and promotes CXCL12-mediated pancreatic cancer cell invasion and metastasis." (PMID 34641806, 2021). "Through increased expression of this ligand in metastatic sites of pancreatic cancer, CXCL12 is also thought to have a cancer cell-homing function at the target organs." (PMID 33546207, 2021). "In pancreatic cancer, the CXCL12 is predominantly secreted by CAFs, while its expression in cancer cells is virtually absent." (PMID 33804861, 2021). "As a marker of CAFs, FAP-positive CAFs contribute to immunosuppression by secreting CXCL12 in a pancreatic cancer model, enhancing recruitment of MDSCs via STAT3-CCL2 signaling and promoting the generation of Tregs and TAMs." (PMID 35155199, 2021). "In contrast, in a mouse model of pancreatic cancer, CAFs-derived CXCL12 prevented tumor infiltration by cytotoxic T cells and induced immune evasion keeping the pancreatic tumors “immunologically cold”." (PMID 33096815, 2020). "CXCL12 can potentially serve as a prognostic factor for gastrointestinal malignancies, including hepatocellular carcinoma and pancreatic cancer." (PMID 32228629, 2020). "Recent work indicated that c-Myc regulates pancreatic cancer progression via HIF-1α/CXCL12/CXCR4signaling pathway." (PMID 33363463, 2020). "In a recent study, CXCL12 secreted by cancer cells bound to its receptors and attracted receptor-positive SCs to pancreatic cancer cells, thereby initiating PNI." (PMID 32064233, 2020). "In this study, we showed that ELMO2 knockdown inhibits CXCL12-mediated migration, chemotaxis, adhesion, and invasion of pancreatic cancer cells." (PMID 32292657, 2020). "Inhibiting CXCL12 produced by FAP+ CAFs re-sensitizes pancreatic cancer cells to anti-PDL1 immunotherapy." (PMID 32466266, 2020). "Wnt signaling plays a pivotal role in CXCL12-induced tumor cell proliferation, as silencing CXCL12/CXCR4 signaling influences pancreatic cancer cell phenotypes and inhibits tumor cell proliferation in vitro via inactivation of the canonical Wnt pathway." (PMID 33363463, 2020).
pancreatic cancer (continued). "Another pathway that contributes to metastasis formation in pancreatic cancer is the C-X-C motif chemokine ligand 12 (CXCL12)/C-X-C chemokine receptor type 4 (CXCR4) axis." (PMID 32069809, 2020). "In this study, we investigated the role of ELMO2 and CXCL12 in pancreatic cancer using cancer cell lines." (PMID 32292657, 2020). "M2 differentiation is induced by CAF-secreted molecules such as Chitinase 3 Like 1 (Chi3L1), C-X-C motif chemokine 12 (CXCL12) and interleukin 6 (IL-6) in breast, prostate and pancreatic cancers, respectively." (PMID 33066357, 2020). "In summary, we showed that ELMO2 plays an essential role in CXCL12-mediated chemotaxis, migration, and invasion of human pancreatic cancer lines." (PMID 32292657, 2020). "According to the colocalization analysis performed on a pixel by pixel basis, Gαi2 and ELMO2 were clearly found to co-localize on the plasma membrane after CXCL12 stimulation of pancreatic cancer cells." (PMID 32292657, 2020). "CXCL12 interaction with its receptor, CXCR4, causes intracellular actin polymerization, which is necessary for pancreatic cancer cell migration and invasion." (PMID 32292657, 2020). "In pancreatic stellate cells, Galectin-1 was observed to induce CXCL12 secretion by activating NF-κB signaling pathway, thereby increasing pancreatic cancer metastasis." (PMID 33363463, 2020). "We found that stimulation with CXCL12 induces a noticeable increase in F-actin in pancreatic cancer cells, which can be prevented by ELMO2 knockdown." (PMID 32292657, 2020). "In other types of malignancies such as osteosarcoma, melanoma and pancreatic cancer, CXCL12 affects both cytotoxic and memory T cells." (PMID 33096815, 2020). "Knocking down of c-Myc significantly decreased CXCL12 expression and inhibited the invasion of pancreatic cancer cells." (PMID 33363463, 2020). "Activated PSCs (equivalent of CAFs in pancreatic cancer) secrete chemokines such as CXCL12 to sequester CD8+ T cells from accessing tumor cells." (PMID 31462327, 2019). "As reported, CXCL12/SDF-1 can enhance the invasive ability of the human pancreatic cancer cell PANC-1 by up-regulating the expression of vascular endothelial growth factor and MMP-9." (PMID 31754081, 2019). "It has been reported that antibodies targeting fibroblast-derived CXCL12 and PD-L1 can synergistically treat pancreatic cancer." (PMID 31998637, 2019). "It has been reported that the activation of NF-kB in pancreatic stellate cells prevents the infiltration of cytotoxic T cells by upregulating CXCL12 in pancreatic cancer." (PMID 31998649, 2019). "In conclusion, data show that CXCL12/CXCR4/ACKR3 axis is involved in keeping the communication between pancreatic cancer and its microenvironment." (PMID 31275385, 2019). "CXCL12, in conjunction with its receptor, has been reported to promote pancreatic cancer development, invasion, and metastasis through the management of the tumor microenvironment via a complex crosstalk with other pathways." (PMID 31304688, 2019). "In pancreatic cancer, inhibition of the CXCL12/CXCR4 axis arrested cell growth and abrogated gemcitabine resistance as well as reduced tumor growth in animal models by blocking CXCR4-dependent mast cell migration." (PMID 30813533, 2019). "Reducing CXCL12 produced by fibroblasts, which mediates immunosuppressive effect in pancreatic cancer." (PMID 30294272, 2018). "CXC chemokine ligand 12 (CXCL12) secreted by PSCs has the ability to reduce the migration of CD8+ T cells into the peritumoral stroma of pancreatic cancer." (PMID 30060755, 2018). "In this study, we demonstrated that SDF-1, also known as C-X-C motif chemokine 12 (CXCL12), secreted by CAFs upregulated SATB-1 expression in pancreatic cancer cells via the SDF-1/CXCR4 axis." (PMID 30337520, 2018). "In this regard, a recent publication demonstrated that targeting CXCL12 from FAP-expressing CAFs with AMD3100 (Plerixafor) synergizes with anti-PD-L1 immunotherapy in pancreatic cancer." (PMID 29545811, 2018).
pancreatic cancer (continued). "The results from both in vitro and in vivo studies have revealed that the stroma-induced CXCL12/CXCR4 axis is involved in pancreatic cancer metastasis through migration, invasion, and angiogenesis/lymphangiogenesis." (PMID 25679210, 2015). "In this study, we show that the CXCL12/CXCR4 axis plays a pivotal role in the neurotropism of pancreatic cancer cells to local peripheral nerves." (PMID 25605248, 2015). "The results showed that the activation of the CXCL12/CXCR4 axis significantly increased pancreatic cancer cells invasion and promoted the outgrowth of the dorsal root ganglia." (PMID 25605248, 2015). "Endogenous or autocrine CXCL12 expression disrupted the ability of pancreatic cancer cells to migrate and home to distant sites of metastasis." (PMID 24594697, 2014). "In serum-free conditions,an increase in apoptosis was detected in adherent CXCL12-expressing pancreatic cancer cells when compared with GFP-expressing controls, though this response was attenuated with the addition of serum." (PMID 24594697, 2014). "Using propidium iodide staining, we measured a ∼50% decrease in the percent of CXCL12-expressing pancreatic cancer cells in the G2 phase of cell cycle, compared to GFP-expressing controls." (PMID 24594697, 2014). "Relative to healthy exocrine ducts, CXCL12 expression was pathologically repressed in pancreatic cancer tissue specimens and patient-derived cell lines." (PMID 24594697, 2014). "In their prior report,Liang and colleagues used an immunostaining amplification kit to report elevated levels of CXCL12 in human pancreas cancer." (PMID 24594697, 2014). "These in vitro data indicate that the overall malignant potential of pancreatic cancer cells,both in the ability of these cells to migrate and evade substrate adhesion, is decreased following reintroduction of the CXCL12 transcript into PDAC cells." (PMID 24594697, 2014). "Since our studies target pancreatic cancer, we examined CXCL12 signaling within the framework of K-Ras." (PMID 22472349, 2012). "The level of CXCL12 mRNA was low in tumor tissues and moderate in the normal pancreas, while expression of CXCL12 was found in pancreatic cancer." (PMID 23181100, 2012). "Moderate expression of CXCL12 was observed in the paracancerous tissues adjacent to the pancreas at the mRNA level, and this was significantly different from that of the pancreatic cancer group (P<0.05)." (PMID 23181100, 2012). "In pancreatic cancer cell lines we determined that chloroquine and hydroxychloroquine block CXCL12-mediated signaling through the ERK pathway with downstream effects on both apoptosis and cell proliferation." (PMID 22319600, 2012). "We previously investigated CXCL12 signaling in pancreatic cancer cells and observed enhanced cell proliferation mediated by the MAPK pathway." (PMID 22472349, 2012). "Previous studies have characterized the effects of chemokine CXCL12 in many cancers including its role in promoting local invasion and distant metastasis of pancreatic cancer." (PMID 22472349, 2012). "Here, our objective was to investigate the roles of CXCR4 and CXCR7 in CXCL12-driven activation of the MAPK pathway in human pancreatic cancer cells." (PMID 22472349, 2012). "To determine if CXCL12 exposure results in changes in pancreatic cancer cell proliferation, we exposed cells to CXCL12 and CXCL11 for 72 h." (PMID 22472349, 2012). "Our results suggest that the development of therapies based on inhibiting CXCL12 signaling to halt the growth of pancreatic cancer should be focused at the ligand level in order to account for the contributions of both receptors to this signaling pathway." (PMID 22472349, 2012). "The rate of positive expression of CXCL12 was lower in the pancreatic tumor tissues compared with the positive rate in the other tissues." (PMID 23181100, 2012). "Our data also suggest that the CXCL12/CXCR4 axis is associated with the formation of lymphatic vessels and blood vessels induced by pancreatic cancer cells." (PMID 23181100, 2012).
pancreatic cancer (continued). "For patients with pancreatic carcinoma, CXCL12 expression was reduced in tumor tissues, but significant levels were detected in paracancerous tissues, normal pancreas and lymph nodes." (PMID 23181100, 2012). "Interactions between CXCR4 and its ligand, CXCL12, promote the survival of breast, pancreatic cancers, and melanoma." (PMID 21539750, 2011). "The pancreatic cancer cells treated with gemcitabine exhibited reduced cytotoxicity in the presence of CXCL12 as compared with the cells treated with drug alone." (PMID 21045835, 2010). "We have investigated the effect of CXCL12 in restricting the gemcitabine-induced toxicity of pancreatic cancer cells and activation of survival signalling pathways." (PMID 21045835, 2010). "Our data demonstrate that CXCL12 induces a series of signalling events in pancreatic cancer cells and counteracts the cytotoxic effects of gemcitabine." (PMID 21045835, 2010). "Our data showed that the expression of Bcl-2, Bcl-xL, Notch-1, and survivin proteins was significantly induced in response to CXCL12 treatment of pancreatic cancer cells." (PMID 21045835, 2010). "Pretreatment with AMD3100 abolished the CXCL12-induced cell signalling, growth promotion, and chemoresistance of pancreatic cancer cells." (PMID 21045835, 2010). "Our data show that CXCL12 treatment induced significant resistance (P<0.01) to gemcitabine cytotoxicity in both pancreatic cancer cell lines tested." (PMID 21045835, 2010). "Pancreatic cancer cells (Panc1 and MiaPaCa) were briefly treated with CXCL12 (5–30 min), and activation of FAK, Akt, and ERK was examined by immunoprobing of total protein with phospho-form-specific antibodies." (PMID 21045835, 2010). "We further tested the growth responsiveness of pancreatic cancer cells to CXCL12 stimulation in two poorly differentiated pancreatic cancer cell lines, MiaPaCa and Panc1." (PMID 21045835, 2010). "Although our data indicated minimal expression of CXCL12 by pancreatic cancer cells, it is reported to be expressed at high levels by stromal cells and at sites of pancreatic cancer metastasis." (PMID 21045835, 2010). "Effect of CXCR4 activation by CXCL12 on restricting the gemcitabine-induced cytotoxicity and stimulating the survival signalling was examined in pancreatic cancer cells by MTT, DNA laddering, caspase activity, immunoblot, and promoter-reporter assays." (PMID 21045835, 2010). "CXCL12, which is produced in a high level in the LN and the liver can initiate and facilitate the homing of pancreatic cancer cells in these tissues." (PMID 19352387, 2009). "The CXCR4/CXCL12 system operates probably as a paracrine loop to enhance the malignancy of pancreatic cancer cells." (PMID 19352387, 2009). "CXCL12 stimulates induction of both migration and invasion of pancreatic cancer cells, AsPC-1, PANC-1 and SUIT-2, in dose-dependent manners in vitro." (PMID 19787093, 2008). "IL-6 and CXCL12 have been reported to delay the early diagnose of pancreatic cancer in mice." (PMID 40248695, 2025). "IL-6 and CXCL12 have been reported to delay the early diagnose of pancreatic cancer." (PMID 40248695, 2025). "This may be the case, e.g., for CXCL8 and CXCL12, which have previously been found to cooperate in stimulating the invasion and proliferation of pancreatic cancer cells." (PMID 39595551, 2024). "Furthermore, the IL-6 autocrine loop, facilitated by Akt and ERK signaling pathway activation, contributes to CXCL12-induced gemcitabine chemoresistance in pancreatic cancer cells." (PMID 38818409, 2024). "In contrast, estrogen may affect CXCL12 production by CAFs, therefore, immune evasion because CXCL12 production by FAP-positive CAFs in pancreatic cancer can induce immune evasion." (PMID 37509283, 2023). "In addition, they suggested some approaches for blocking Cxcl12 in pancreatic tumour cells, in order to increase antitumor immunity." (PMID 35180880, 2022).
pancreatic cancer (continued). "Furthermore, in lung and pancreatic tumors, the secretion of CXCL12/SDF1 by CAFs contributes to the exclusion of T cells from the cancer cell proximity." (PMID 36338519, 2022). "In addition to potentiating growth and migration, CXCL12 has been shown to protect pancreatic cancer cells from the cytotoxic effects of the PDAC standard-of-care drug gemcitabine." (PMID 35008248, 2021). "However, CXCL12 was also but less expressed by stromal cells presumably fibroblasts as seen in a murine pancreatic cancer model." (PMID 33988305, 2021). "In the sections below, we focus on approaches to targeting the CXCL12 axis in pancreatic cancer." (PMID 35008248, 2021). "It was reported that CQ could decrease pancreatic cancer stem cells via inhibition of CXCL12/CXCR4 signaling." (PMID 34733155, 2021). "The latest data suggest that inhibiting the interaction between CXCR4 expressing T cells and CXCL12 secreting cells in the microenvironment may modulate anti-CTLA-4 or anti-PD-1 immunotherapy in pancreatic cancer and HCC." (PMID 33790943, 2021). "These pro-oncogenic functions of CXCL12 make it an attractive target in pancreatic cancer." (PMID 35008248, 2021). "FAP+ CAFs are the primary pancreatic cancer source of the chemokine ligand 12 (CXCL12)." (PMID 32466266, 2020). "Targeting stroma in a murine model of metastatic pancreatic cancer using the immune modulating effect of hyaluronan degradation by PEGPH20 significantly decreased the immunosuppressive effect of CXCL12/CXCR4/CCR7 signaling axis in CAFs, myeloid, and CD8+ T cells." (PMID 32466266, 2020). "Interestingly, the administration of CXCL12 in pancreatic cancer cells showed also the activation of signaling pathways mediated by ACKR3, which, therefore, has not only a scavenger role for CXCL12." (PMID 31275385, 2019). "Furthermore, an interesting work showed that CXCL12 RNA expression and protein secretion levels were increased when fibroblasts were cocultured with gemcitabine-treated pancreatic cancer cells resistant to gemcitabine." (PMID 31275385, 2019). "Most of the studies have assigned a protumoral role to CXCL12 in several cancer types, but a study demonstrated that CXCL12 could play also an antitumor role in pancreatic cancer." (PMID 31275385, 2019). "Moreover, circulating TIMP1-activated HSCs express C-X-C motif chemokine 12 (CXCL12), which induces MDSC and neutrophil migration through CXCR4 and creates a microenvironment in the liver that increases its susceptibility to pancreatic tumor cells." (PMID 30792719, 2019). "Moreover, in stellate cells obtained from primary pancreatic cancer tissues, the protein Galectin-1 is involved in stimulating the production of CXCL12 through the activation of NF-κB." (PMID 31275385, 2019). "Also in pancreatic cancer it has been shown that the interaction between tumor and surrounding stroma, mediated by the CXCL12/CXCR4 axis, influences the tumor growth and its aggressiveness." (PMID 31275385, 2019). "Consequently, blocking the CXCL12/CXCR4 axis improved immuno-oncological approaches such as checkpoint inhibition in models of pancreatic cancer and hepatocellular cancer." (PMID 30813533, 2019). "In pancreatic cancer, it has been demonstrated that the chemokine CXCL12 could play both protumor and antitumor roles." (PMID 31275385, 2019). "Indeed, recently in pancreatic cancer, the CXCR4/CXCL12 axis has been linked to the resistance to immune checkpoint therapy." (PMID 29222645, 2018). "Finally, the secretion of CXCL12/SDF-1 by CAFs from lung and pancreatic tumors can contribute to the exclusion of T cells from the cancer cell proximity." (PMID 29545811, 2018). "A previous study revealed that CXCL12 specifically signals through CXCR4, a member of the GPCRs to activate Akt and ERK and subsequently phosphorylate IκBα, causing activation of NF-κB signaling in pancreatic cancer cells." (PMID 28288630, 2017).